SIRT6 (sirtuin 6)
Diseases named in the same sentence as SIRT6 in open-access papers (continued):
Sharing a sentence is not in itself a finding about the gene and the disease.
glomerulosclerosis (2 papers, 2017 to 2020). A hardening of the kidney glomerulus caused by scarring of the blood vessels. "Deletion of Sirt6 also attenuated the protective effect of cyclodextrin (CD) on Ang II-induced urinary albumin excretion, glomerulosclerosis and podocyte injury." (PMID 32642006, 2020). "ADR-treated Cre+/Sirt6fl/fl mice exhibited significant increases in urinary albumin excretion, glomerulosclerosis and podocyte injury, and marked decreases in the levels of nephrin and podocin compared with the ADR-treated Cre+/Sirt6+/+ mice." (PMID 28871079, 2017). "Moreover, the deletion of Sirt6 did not affect the protective effect of SV against Ang II-induced increases in urinary albumin excretion, glomerulosclerosis and podocyte injury." (PMID 32642006, 2020). "In addition, we found that deletion of Sirt6 did not affect the protective effect of SV on Ang II-induced urinary albumin excretion, glomerulosclerosis or podocyte injury." (PMID 32642006, 2020).
head and neck squamous cell carcinoma (2 papers, 2019 to 2021). A squamous cell carcinoma that arises from any of the following anatomic sites: lip and oral cavity, nasal cavity, paranasal sinuses, pharynx, larynx, and salivary glands. "In this study, we focused on cell death in association with Sirt6/Sirt1 and reactive oxygen species (ROS) in head and neck squamous cell carcinomas (HNSCCs)." (PMID 33727672, 2021).
Hepatic failure (2 papers, 2022 to 2024). "To assess the relevance of Sirt6 to human liver failure, we analyzed Sirt6 expression using immunohistochemistry analysis in hepatic tissues from individuals with disease-associated liver failure who required liver transplantation." (PMID 38649362, 2024). "Sirt6 levels were significantly decreased in the liver of hepatic failure patients compared to those from healthy subjects." (PMID 38649362, 2024). "Since all three mouse models share similar phenotypes, which are characterized by hepatic inflammation, oxidative stress, and necrosis, it is conceivable to speculate that Sirt6 might have protective action on various conditions of liver failure." (PMID 38649362, 2024). "To confirm the protection of Sirt6 on liver failure, we then examined the role of hepatic Sirt6 on BDL-induced liver injury, we performed BDL in both Control mice and Sirt6-HepTg mice that were sacrificed at 1, 3, and 7 days after surgery." (PMID 38649362, 2024). "However, the regulatory effects of SIRT6 in oxidative stress of liver failure are still unknown." (PMID 35517808, 2022). "Although SIRT6 plays an important role in several disease models, there is no report on the effect of SIRT6 on the liver failure model." (PMID 35517808, 2022). "However, there is no relative study on whether SIRT6 regulates the liver inflammation by inhibiting the NF-κB pathway in liver failure." (PMID 35517808, 2022).
IgA nephropathy (2 papers, 2017 to 2022). "We also examined intra-renal expression levels of Sirt1, Sirt3, Sirt6, and Nmnat1 in specimens from patients with IgA nephropathy." (PMID 35962139, 2022). "Intra-renal expression levels of Sirt1, Sirt3, Sirt6, and Nmnat1 were evaluated in specimens from 27 patients who were histologically diagnosed with FSGS and IgA nephropathy." (PMID 35962139, 2022). "Importantly, the Sirt6 level was also markedly reduced in renal biopsies from patients with other different forms of podocytopathies such as MGN (n = 8) and IgA nephropathy (n = 9)." (PMID 28871079, 2017).
intracerebral haemorrhage (2 papers, 2023). "Additionally, SIRT6’s beneficial and protective effects have been reported in skin wound healing using MDL-800, a selective SIRT6 activator, as well as in neurological recovery after intracerebral haemorrhage in a rat model." (PMID 38016059, 2023).
left ventricular hypertrophy (2 papers, 2023 to 2025). Enlargement of the LEFT VENTRICLE of the heart. "In a cardiac‐specific SIRT6 knockout mouse model fed a high‐fat diet (HFD), loss of SIRT6 function exacerbates cardiac injury, including left ventricular hypertrophy and lipid accumulation." (PMID 37143582, 2023).
memory impairment (2 papers, 2018 to 2025). "Contextual fear memory was elevated by SIRT6 depletion, contrary to a previous report showing memory impairment following genetic SIRT6 inactivation in neuronal progenitors." (PMID 30189861, 2018). "However, since the other group targeted total neuronal populations rather than excitatory neurons, the discrepancy may be attributable to SIRT6 depletion in inhibitory neurons resulting in memory impairments." (PMID 30189861, 2018).
muscle atrophy (2 papers, 2017 to 2022). The loss of muscle tissue due to inactivity or disease. "Taken together, these data indicated that up-regulation of SIRT6 in cachectic conditions helped to block the muscle-wasting state, thus highlighting a new promising role for SIRT6 in prevention of muscle atrophy." (PMID 28928419, 2017). "To explore the clinical relevance of these findings, we tested whether pharmacological inhibition of SIRT6 could be used to protect mice against Dex-induced muscle atrophy." (PMID 36109503, 2022).
retinal degeneration (2 papers, 2017 to 2023). Degeneration of the retina. "Oxidative injury has been shown to play an important role in retinal degeneration including age-related retinal disease, and it is possible that this is one of the mechanisms leading to the accelerated retinal degradation observed in the SIRT6 KO mice." (PMID 28448551, 2017). "The decrease noted in SIRT6 KO by 6 and 10 months exceeds these levels, but interestingly, both the functional and the structural degradation are much less severe than those seen in genetically-determined retinal degenerations such as in rd10 mice." (PMID 28448551, 2017).
retinal disease (2 papers, 2017 to 2023). "This situation provides eye researchers with an advantage of learning from findings in other tissues, as well as a great opportunity to quickly test available SIRT6 modulators in retinal disease models, including culture cells, retinal organoids, and animal models." (PMID 38016059, 2023). "Considering the protective effects of SIRT6 to retina function and retinal aging, further investigation of the post-transcriptional regulation of Sirt6 expression and its role in retinal disease is needed." (PMID 29249955, 2017).
sarcoma (2 papers, 2018 to 2021). A usually aggressive malignant neoplasm of the soft tissue or bone.
serous adenocarcinoma (2 papers, 2018 to 2019). An adenocarcinoma that is characterized by the presence of papillary patterns and cellular budding. "Nu-SIRT6 positivity predicted a 1.905-fold (95% CI; 1.030–3.524) greater risk of death of high-grade serous carcinoma patients." (PMID 30524965, 2018). "SIRT6 was expressed at higher levels in all types of OC than it was in normal tissues in Hendrix’s dataset except for serous adenocarcinoma." (PMID 31572453, 2019). "In 63 high-grade serous carcinomas, the factors included in the multivariate analysis were age, tumor stage, Nu-SIRT6 expression, and Nu-Aβ-catenin expression." (PMID 30524965, 2018). "The factors significantly associated with OS or RFS by univariate analysis in 63 high-grade serous carcinomas were age of patients, tumor stage, Nu-SIRT6 expression, and Nu-Aβ-catenin expression." (PMID 30524965, 2018).
subarachnoid hemorrhage (2 papers, 2019 to 2026). A serious neurological disorder characterized by intracranial hemorrhage into the subarachnoid space. "Bexa, bexarotene; UVI3003, a specific RXR antagonist; OSS128167, a selective SIRT6 inhibitor; Scr siRNA, Scramble siRNA; SAH, subarachnoid hemorrhage." (PMID 30791908, 2019).
tendinopathy (2 papers, 2022 to 2025). "Both in rat cultured tenocytes and in Achilles’ tendons with collagenase-induced tendinopathy levels of IL6, ROS and NOX1 and NOX4 were increased while SIRT1 and SIRT6 were decreased together with SOD activity." (PMID 40023978, 2025). "In Achilles tendons with collagenase-induced tendinopathy, NMN increased the mRNA expression of SIRT1 and SIRT6, as well as SOD activity; while suppressing protein expression of NOX1 and NOX4, and mRNA expression of IL6." (PMID 35287653, 2022).
thoracic aortic aneurysm (2 papers, 2023 to 2024). An aneurysm formed in the wall of the proximal portion of the descending aorta proceeding from the arch of the aorta. "Studies have shown that SIRT1 and SIRT6 reduces abdominal or thoracic aortic aneurysms by reducing the senescence and inflammation in VSMCs." (PMID 38673941, 2024).
thrombosis (2 papers, 2023 to 2025). "SIRT6 knockdown increases TF expression and initiates pro-inflammatory pathways, protecting endothelium SIRT6 from experimental arterial thrombosis." (PMID 41567643, 2025). "Coincidentally, a recent study demonstrated that endothelium-specific SIRT6 deletion promotes arterial thrombosis in mice by enhancing TF expression and activating pro-inflammatory signaling." (PMID 38186648, 2023). "Recently, a study revealed that targeted deletion of SIRT6 in the endothelium of mice promotes arterial thrombosis by increasing TF expression and activating pro-inflammatory signaling, highlighting the importance of SIRT6 in regulating thrombotic processes." (PMID 38186648, 2023).
thymic atrophy (2 papers, 2017 to 2021). "We found that Sirt6 deficient in TECs caused severe thymic atrophy and that the proliferation, maturation and function of mTECs were drastically affected by Sirt6 deletion." (PMID 33869219, 2021).
thyroid tumor (2 papers, 2020 to 2021). A benign or malignant neoplasm affecting the thyroid gland. "However, in tumors, particularly thyroid tumors, the role of SIRT6 in regulating these two effects remains unclear." (PMID 32983963, 2020). "Thyroid tumors acquired aggressive phenotype and epithelial-mesenchymal transformation(EMT) via sirtuin 6 (SIRT6)-Autophagy-Warburg Effect Axis." (PMID 34926283, 2021).
acute leukemia (1 paper, 2014). A clonal (malignant) hematopoietic disorder with an acute onset, affecting the bone marrow and the peripheral blood. "The region on chromosome 19 where SIRT6 is located is frequently affected by chromosomal alterations in acute leukemia." (PMID 25541994, 2014).
Age-related cataract (1 paper, 2024). A type of cataract (opacification of the lens) that forms during the course of aging. "A recent study reported that melatonin suppresses ferroptosis by regulating the SIRT6/p-Nrf2/GPX4 and SIRT6/NCOA4/FTH1 pathways in age-related cataract." (PMID 39519165, 2024).
age-related macular degeneration (1 paper, 2023). Age-related loss of vision in the central portion of the retina (macula), secondary to retinal degeneration. "As described later, this SIRT6 function is connected to the concept of the photoreceptor–RPE energy ecosystem and therefore has implications in retinal degenerative diseases such as retinitis pigmentosa (RP) and age-related macular degeneration (AMD)." (PMID 38016059, 2023).
anaphylaxis (1 paper, 2022). An acute hypersensitivity reaction that occurs from exposure to an allergen. "Read in light of the results obtained through earlier studies 12, 37, 41-43, our findings point to a potential use of NAD+ precursors in conjunction with Sirt6 activation as a therapeutic option for inflammatory disorders, including anaphylaxis." (PMID 35547746, 2022).
Arterial thrombosis (1 paper, 2023). The formation of a blood clot inside an artery. "In this study, we demonstrate that SIRT6 is expressed in mouse platelets and negatively regulate thrombin-induced platelet activation and FeCl3-induced arterial thrombosis in mice." (PMID 38186648, 2023). "Moreover, in platelet adoptive transfer experiments between wild-type (WT) and SIRT6−/− mice, the loss of SIRT6 in platelets significantly prolongs the mean thrombus occlusion time in a FeCl3-induced arterial thrombosis mouse model." (PMID 38186648, 2023). "Moreover, by using a FeCl3-induced arterial thrombosis mouse model, we confirmed the protective effect of SIRT6 in the reduction of thrombus occlusion time and thrombus area." (PMID 38186648, 2023). "To investigate the role of SIRT6 in thrombosis, we first performed a FeCl3-induced arterial thrombosis model in C57BL/6 mice and examined the effect of SIRT6 activation on thrombosis by intraperitoneal injection of the specific SIRT6 agonist, UBCS039." (PMID 38186648, 2023). "In contrast, activation of SIRT6 through specific agonist treatment (UBCS039) confers a pronounced protective effect on platelet activation and arterial thrombosis." (PMID 38186648, 2023).
arteriosclerosis (1 paper, 2023). A vascular disorder characterized by thickening and hardening of the walls of the arteries. "The expression of Sirt6 in macrophage foam cells was examined in atherosclerotic plaques from ApoE−/− mice fed a western diet for 16 weeks to determine if macrophagic Sirt6 involved in the progression of arteriosclerosis." (PMID 37736721, 2023).
astrocytoma (1 paper, 2020). "Unlike the literature data, our extract reduces both Sirt6 and Sirt7 expression in astrocytoma cells." (PMID 32727075, 2020).
ataxia telangiectasia (1 paper, 2024). Ataxia-telangiectasia is the association of severe combined immunodeficiency (affecting mainly the humoral immune response) with progressive cerebellar ataxia. "For example, overexpression of SIRT6 instead of Rad51 or NBS1 rescues HR repair in ageing cells, and restoration of the NAD+/SIRT1 pathway improves healthspan in Ataxia-telangiectasia models via mitophagy and DNA repair." (PMID 39394181, 2024).
autoimmune disorder of the central nervous system (1 paper, 2020). "Given the role for SIRT6 in lymphocyte and dendritic cell activation, we evaluated the effect of the SIRT6 inhibitor, compound 1 in a Th1/Th17-driven model of autoimmune disorder of the central nervous system (CNS), such as EAE." (PMID 32736564, 2020).
autoimmune disorders (1 paper, 2020). "Thus, based on SIRT6 role in inflammation and in DC, we decided to test the SIRT6 inhibitor, 1, in the EAE model of autoimmunity according to both a “preventive” and a “therapeutic” protocol." (PMID 32736564, 2020).
bladder urothelial cancer (1 paper, 2020). "The same analysis was also performed in a TCGA bladder urothelial cancer cohort and a similar SIRTs expression profile was found, with IHG showing significantly increased SIRT4 expression levels comparing to PLG, whereas SIRT5 and SIRT6 expression levels were decreased." (PMID 32344886, 2020).
Bowen Disease (1 paper, 2024). "However, SIRT6 expression was slightly higher in Bowen Disease (BD) than in CSCC tissue, which may be related to the limited number of BD tissue samples." (PMID 38548549, 2024).
brain malformations (1 paper, 2026). "In our study, two triplet siblings carried compound heterozygous variants in SIRT6, presented with epilepsy and brain malformations, and two met criteria for DRE." (PMID 41563000, 2026).
cerebral infarct (1 paper, 2022). "In a murine model of acute ischemic stroke, SIRT6 knockdown resulted in larger cerebral infarct size, worse neurological outcome, and higher mortality, indicating a possible neuro-protective role of SIRT6." (PMID 36443316, 2022).
Cirrhosis (1 paper, 2020). A chronic disorder of the liver in which liver tissue becomes scarred and is partially replaced by regenerative nodules and fibrotic tissue resulting in loss of liver function. "SIRT6 is downregulated in cirrhosis, and HCC and Sirt6-/- hepatocytes expressed an HCC gene signature." (PMID 32443737, 2020).
cognitive decline (1 paper, 2021). "Interestingly, the top two categories downregulated in SIRT6-KO mice brains are brain-related (cell-cell interaction and neuronal system), and the learning cluster was also affected by SIRT6-KO – which indicates the cognitive decline of these mice." (PMID 33690173, 2021).
complication (1 paper, 2020). Any disease or disorder that occurs during the course of, or because of, another disease, treatment, or procedure. "Besides, except for SIRT1, there are still other members of the sirtuin family (e.g., SIRT3, SIRT6, and SIRT7) that are active in modulating vascular function, which inspires further works to investigate their associations with oxidative stress and diabetic vascular complications." (PMID 33304318, 2020).
Corneal opacity (1 paper, 2018). A reduction of corneal clarity. "Our findings that Sirt6 deficiency results in corneal keratitis and corneal opacity using both an in vivo corneal wound healing model and during aging provide further evidence that sirtuins are responsible for the maintenance of corneal homeostasis and function." (PMID 30070973, 2018). "In an in vivo corneal epithelial wound healing model, Sirt6 deficiency resulted in delayed and incomplete wound healing and was associated excessive inflammation in the corneal stroma and dysfunction of Notch signaling, leading to keratinization of the corneal epithelium and corneal opacity." (PMID 30070973, 2018).
coronary artery atherosclerosis (1 paper, 2025). "This study developed a nomogram to demonstrate the functionality of SIRT6 in assessing severity of coronary artery atherosclerosis." (PMID 39851250, 2025).
dengue virus infection (1 paper, 2021). "Similarly, SIRT-6 expression is upregulated in RAW 264.7 macrophages following dengue virus infection – mechanistically, the shRNA-mediated knockdown of SIRT-6 exacerbates virus-mediated pro-inflammatory cytokine production including IL-6 and TNF-α via a NF-κB p65 subunit mechanism." (PMID 34485381, 2021).
dialysis (1 paper, 2024). "However, the relationship between SIRT6 and peritoneal fibrosis (PF) in peritoneal dialysis (PD) remains unclear." (PMID 38483736, 2024). "There is no research on whether SIRT6 is related to peritoneal dialysis-related peritoneal dysfunction." (PMID 38483736, 2024).
emphysema (1 paper, 2023). "SIRT6 has been shown to reduce emphysema by inhibiting matrix metalloproteinases and regulating the expression of several antioxidant genes." (PMID 38203542, 2023).
endometriosis (1 paper, 2021). The growth of functional endometrial tissue in anatomic sites outside the uterine body. "Related to clinical parameters, SIRT6 was correlated positively with FSH and LH doses administered in endometriosis patients." (PMID 34356330, 2021).
endotoxemia (1 paper, 2019). "Consequently, the increased expression of SIRT6 in SIRT2/3−/− macrophages may favor FAO and contribute to dampen the cytokine storm involved in the pathological process of endotoxemia." (PMID 31849939, 2019).
Epstein-Barr virus infection (1 paper, 2023). An infection that is caused by Epstein-Barr virus. "Specifically, SIRT6 was enriched in thermogenesis, while PSMD14 and PSMC6 were enriched in Epstein-Barr virus infection, and NCBP2 and PYM1 were enriched in nucleocytoplasmic transport." (PMID 37958518, 2023).
Friedreich ataxia (1 paper, 2022). An inherited condition that affects the nervous system and causes movement problems. "To determine if the genotype of SIRT6 is related to the severity of clinical features of FRDA, we analyzed modified Friedreich Ataxia Rating Scale (mFARS) scores, a composite measure of neurological dysfunction in FRDA." (PMID 36133907, 2022).
gastrointestinal adenomas (1 paper, 2021). "Nevertheless, the prevalence of gastrointestinal adenomas was significantly lower in SIRT6-tg and SIRT1 + 6-tg mice both at 25 months of age and at natural death." (PMID 34050173, 2021).
glaucoma (1 paper, 2024). Increased pressure in the eyeball due to obstruction of the outflow of aqueous humor. "Similarly, SIRT-6 overexpression has been shown to be protective in glaucoma models, as has Tau protein modulation, among others." (PMID 39201561, 2024).
hearing loss (1 paper, 2024). "SIRT4, SIRT5, and SIRT6 lacked any evidence of involvement in hearing loss, but their expressions were slightly altered in an ARHL model of mice in various tissue types of an ARHL model of mice." (PMID 39204103, 2024).